NOS1 (nitric oxide synthase 1)
Diseases named in the same sentence as NOS1 in open-access papers (continued):
Sharing a sentence is not in itself a finding about the gene and the disease.
tumor (53 papers, 1998 to 2026). "In previous studies, NOS1 is overexpressed in various types of cancer, and its expression is associated with tumor progression." (PMID 35807116, 2022). "In the tumor microenvironment, pro-tumorigenic cancer associated fibroblasts upregulate NOS1 together with nuclear factor erythroid 2-related factor 2 (NRF2) and hypoxia inducible factor 1α (HIF1α)." (PMID 34200849, 2021). "PFKM-C351S mutation reduced the size and weight of tumors compared to those of PFKM-WT tumor, and NOS1 promotion of tumor reduced by PFKM-C351S mutation." (PMID 33859186, 2021). "NOS1 upregulation was found to support the growth and activity of cultured cancer-associated fibroblasts, which are known to stimulate tumor progression." (PMID 30082427, 2018). "The comprehension of the molecular mechanisms underlying the regulation of metabolism and immune by NOS1 induced S-nitrosylation may lead to new therapeutic strategies to control tumor progresses." (PMID 33859186, 2021). "Some genes in the overall sample group could be related to tumor progression in association with patient survival; only NOS1, TCP1, and DKFZp564N2472 had higher expression levels in patients with lower survival, while the remaining genes had lower expression levels in these patients." (PMID 29285214, 2017). "We used the UCSC Xena database to comparatively analyze NOS1 expression and methylation status between tumour and adjacent normal tissues across 33 cancer types." (PMID 42048609, 2026). "Crucially, pharmacological inhibition of NOS1 with Nω-propyl-L-arginine selectively curbed tumor growth in hypercholesterolemic models, suggesting a therapeutic strategy with reduced off-target toxicity." (PMID 41268067, 2025). "Neuronal NOS (nNOS/NOS1) has emerging evidence suggesting a role in neuronal-like signaling within the tumor microenvironment." (PMID 41268067, 2025). "The same family member CXCL14 can promote tumor growth by stimulating angiogenesis and recruiting macrophages through nitric oxide synthase 1 (NOS1)." (PMID 37496657, 2023). "We further analyzed the tumor remission by using these 14 NOS1-ISGs in 19 patients under chemotherapy (GSE10282)." (PMID 35538490, 2022). "Here, S-nitrosylated PFKM by NOS1 promoted lactic acid production extracellularly and intracellularly, and reduced macrophages’ infiltration in tumor tissues." (PMID 33859186, 2021). "NOS1 is highly expressed in cancer tissues and usually promotes tumor progression by synthesizing a low level of NO and enhancing cell proliferation, anti-apoptosis, and migration." (PMID 33859186, 2021). "Taken together, these results indicate that NOS1-induced S-nitrosylation of HDAC2 promotes lung metastasis primarily by inhibiting tumor lymphocyte infiltration." (PMID 31805977, 2019). "NOS1 produces constitutively low levels of NO, which generally promote tumor growth, such as cell proliferation, anti-apoptosis and migration, in many cellular processes." (PMID 31805977, 2019). "We report the mechanism by which HDAC2 regulates the expression of ISGs in tumor cells, and NOS1 induces epigenetic changes through S-nitrosylation of HDAC2, thereby leading to dysfunctional IFN signaling and promoting lung metastasis." (PMID 31805977, 2019). "We assessed the expression of NOS1 in tumour samples by using an antibody directed to the C-terminus part of NOS1 on cryostat sections." (PMID 15150612, 2004). "To confirm the staining pattern, we used another antibody directed to the N-terminus part of NOS1, on paraffin sections of a few cases of each type of tumour." (PMID 15150612, 2004). "NOS1 expression and activity were found to be downregulated, correlating with the tumour grade, as shown by immunohistochemistry, quantitative RT–PCR analysis, and histochemical detection of the NADPH-diaphorase activity of nitric oxide synthases (NOS)." (PMID 15150612, 2004). "Here, we showed that NOS1 induces tumor immune escape through S-nitrosylation of IRF7." (PMID 41535256, 2026).
tumor (continued). "Thus, NOS1 inhibition of IFNs signaling activation in tumor cells primarily occurs during the initial phase of cellular response to PRR signaling, rather than through disruption of components in the JAK/STAT1 pathway." (PMID 41535256, 2026). "Deletion of NOS1 leads to down-regulation of innate immune and switching “cold” tumors to “hot”, suggesting NOS1 could be a potential target for tumor immune therapy." (PMID 35538490, 2022). "NOS1 constitutively synthesizes a low level of NO and plays a critical role in tumor progressions." (PMID 33859186, 2021). "However, presence of the NOS1 immunopositive white blood cells was attached to vessel endothelium in tumor growth regions often observed." (PMID 23691268, 2013). "One cannot exclude that high-grade clear cell RCC tumour cells express a specific splicing variant of NOS1 mRNA, which would not have been detected in our experimental conditions." (PMID 15150612, 2004). "Finally, the staining pattern of protein tyrosine nitration, assessed by immunohistochemistry, parallelled that of NOS1 expression in normal renal parenchyma and benign tumours, supporting the concept that protein nitration was accounted for by NOS1 activity." (PMID 15150612, 2004). "However, this enhanced cytotoxicity of IRF7-C435A lymphocytes was reduced by the addition of H2KB antibodies, suggesting that downregulation of antigen presentation is the main mechanism by which NOS1-mediated S-nitrosylation of IRF7 facilitates tumor escape from killing by immune cells." (PMID 41535256, 2026). "Finally, the NOS-1 case lacked any mutation despite a high content of tumor cells (60%); this would be an unusual feature for PCLBCL, LT." (PMID 35452489, 2022). "Thus, S-nitrosylation of PFKM may be dominated by NOS1 and be critical for NOS1 induced tumor promotion in various types of cancer." (PMID 33859186, 2021). "Therefore, we used the biotin-switch assay to test whether NOS1 directly modifies HDAC2 by means of S-nitrosylation in tumor cells." (PMID 31805977, 2019). "Similarly, in our study, NOS2 was never detected by immunohistochemistry in all the tumours tested, thus suggesting that the loss of NOS1 expression was not counterbalanced by induction of NOS2 expression in tumour cells." (PMID 15150612, 2004). "Here, we found that NOS1 expression induces IRF7 modification by S-nitrosylation at the C435 site in mice (C481 in humans), which functionally promoted tumor growth in mouse models." (PMID 41535256, 2026). "Except for NOS1, DNMT1 and CCL5, the hub genes CCL19 and CCR7 in DE-GRGs are compose of the CCL19/CCL21-CCR7 axis that exerts both immune response and tumor proliferation." (PMID 35517412, 2022). "Of therapeutic relevance, targeting CBFB resulted in decreased tumor burden and bone metastasis, downregulation of bone metastasis markers, and impaired regulation of oxidative stress–related proteins NAE1 and NOS1." (PMID 35903297, 2022). "Three isozymes of NOSs: neuronal NOS (NOS1), inducible NOS (NOS2), and endothelial NOS (NOS3), all contribute to tumor progression through distinct effects of biological regulation on tumorigenesis." (PMID 33859186, 2021). "In this study, we found that NOS1 modifies HDAC2 by S-nitrosylation, resulting in increased tumor metastasis in B16F10 mice." (PMID 31805977, 2019). "The Ca2+-dependent NOS activity, which indicates NOS1 and NOS3 expression, was significantly reduced in lung carcinomas compared with adjacent non-tumour tissue (P < 0.004)." (PMID 9683299, 1998). "This suggests that NOS1 induction of IRF7 S-nitrosylation activates antigen-presenting cells (APCs) by increasing the transcription of MHC class I and class II antigens and APM components, thereby reversing immune suppression in the tumor microenvironment." (PMID 41535256, 2026). "Therefore, NOS1-induced IRF7-SNO inhibits T cell activation and T cell killing in the tumor immune microenvironment." (PMID 41535256, 2026).
tumor (continued). "Upon tumour growth, Atrogin1 expression was enriched in specialized MTJ and NMJ myonuclei, which also exhibited distinctive changes in their transcriptomes, including increased Eda expression in MTJ and reduced Deptor and Nos1 expression in NMJ." (PMID 39001644, 2024). "Taken together, we speculate that, via NOS1, CIAPIN1 activates the TGF-β/SMADs signaling pathway to augment tumor metastasis." (PMID 35807116, 2022). "Moreover, STITCH analysis combined with KEGG signaling pathway search revealed that, via NOS1, CIAPIN1 interacted with nine proteins related to cell migration, invasion, and metastasis of tumor cells." (PMID 35807116, 2022). "In contrast, the neuronal Nos1 and the endothelial Nos3 gene transcripts were not significantly regulated by type I IFNs, in either tumor cells or leukocytes." (PMID 31481761, 2019). "Because we found that HDAC2-MUT partially reversed the role of NOS1 in promoting lung metastasis, we further investigated whether HDAC2-MUT directly inhibited tumor growth." (PMID 31805977, 2019). "Whether NOS1 participates in the regulation of the IFNα response through S-nitrosylation of HDAC2 in tumor cells has not been determined." (PMID 31805977, 2019). "In contrary to these observations, tumor vessel endothelium showed no staining for NOS1 antibody." (PMID 23691268, 2013). "Although the genes in (PRKAA2, GNG7, MYL3, NOS1, ADCY1, PLCB1, MYLK3, and MYLK4) the apelin/APJ signaling axis are found to be downregulated and might not be considered responsible in cdRCC progression, downregulation of GNG7 tells a different story due to its tumor‐suppressive activity." (PMID 40304310, 2025).
cancer (45 papers, 2004 to 2026). A tumor composed of atypical neoplastic, often pleomorphic cells that invade other tissues. "Low expression and hypermethylation of NOS1 have been identified in 12 cancer types, with CRC demonstrating this characteristic epigenetic regulation." (PMID 42048609, 2026). "Increasing evidence suggests that NOS1 plays a critical pro-oncogenic role in multiple types of cancer, but little has been related to CRC." (PMID 38755702, 2024). "In the present study, we demonstrate that ARL-17477 exhibits a NOS1-independent pharmacological activity that involves inhibition of the autophagy-lysosomal system and prevents cancer growth in vitro and in vivo." (PMID 37402770, 2023). "The result showed that the glycolysis increased in SKOV3-OE-NOS1 cells and reduced in SKOV3-NOS1-KO cells, indicating that NOS1 is involved in regulating the glycolysis in cancer cells." (PMID 33859186, 2021). "The hierarchical clustering of a class of glycolysis-related genes distinctly separated the normal samples from the cancer samples, and NOS1 was clustered to the group of the glycolysis enzymes that were highly expressed in cancer." (PMID 33859186, 2021). "In contrast, the levels of NOS-1 and -3, the enzymes responsible for production of the basal level of NO in the breast, remained unchanged during cancer progression and, thus, were irrelevant to reduction of NO." (PMID 31040372, 2019). "So we investigated the connection of NOS1 with PFKM related to cancer cell proliferation." (PMID 33859186, 2021). "Moreover, and alternatively, the regulation of autophagy by NOS1 if controlled should be considered as a potential therapeutic strategy for cancer." (PMID 30952837, 2019). "Thus, ARL-17477 is a dual inhibitor of NOS1 and the autophagy-lysosomal system that could potentially be used as a cancer therapeutic." (PMID 37402770, 2023). "Therefore, we investigated both NOS1 and sGC expressions in benign and malignant renal tumours." (PMID 15150612, 2004). "Since we noticed a downregulation of NOS1 expression in most malignant renal tumours, we can suggest that the reactive nitrogen species released by the inflammatory infiltrate are responsible for the heterogeneous nitrated staining pattern observed in these malignant tumours." (PMID 15150612, 2004). "Nitric oxide is a signaling molecule synthesized by three subtypes of NO synthase (NOS1, NOS2, and NOS3) and is increased in various cancers and involved in various cancer processes, such as proliferation and migration." (PMID 38877096, 2024). "Thus, NOS1 expression might shift metabolism of redirect nutrients into anabolic pathways to maintain biomass production for supporting uncontrolled proliferation of cancer cells." (PMID 35538490, 2022). "Nitric oxide, a signaling molecule synthesized by three isoforms of NO synthase (NOS1, NOS2 and NOS3), increases in multiple cancers and participates in various cancer processes such as formation, progression and metastasis." (PMID 31805977, 2019). "Our results imply that inhibition of NOS1 by either genetic or pharmacologic methods can inhibit the AKT/mTOR pathway and decrease chemoresistance displayed by cancer cells." (PMID 28243469, 2017). "Sequencing data from the Sanger and Broad Institutes indicated that none of these cancer cell lines displayed a mutation in ATRX or DAXX, except NOS1 that had a homozygous loss of the ATRX genes." (PMID 35920001, 2022). "Similarly, also the interactions existing between NOS1 and NOSIP have been investigated; however, the functional effects of these interactions in cancer are not fully understood yet." (PMID 35740092, 2022). "Indeed, in the DepMap Portal database, no cancer cell line is considered dependent on NOS1 for survival." (PMID 37402770, 2023). "Furthermore, immunoblot analysis did not detect the expression of NOS1 protein both in the wild-type and NOS1−/− cell lysates, suggesting that the cancer cells express very low to no level of NOS1 protein." (PMID 37402770, 2023).
cancer (continued). "However, NOS1 is mainly expressed in neurons, whereas ARL-17477 affected many non-neuronal cancer cells." (PMID 37402770, 2023).
infection (23 papers, 2010 to 2025). The state of being infected such as from the introduction of a foreign agent such as serum, vaccine, antigenic substance or organism. "NOS1 and CanA showed a similar expression pattern, which were mainly upregulated at 4 and 12 h post infection." (PMID 35663981, 2022). "However, most of these genes, including nitric oxide synthase gene NOS1, were down-regulated at 72 hpi, probably as a result of the effort of the immune system to compensate for the damage that occurred in earlier time-points of the infection." (PMID 35215144, 2022). "NO is produced from L-arginine by three NO synthases (NOS1, NOS2 and NOS3) and NOS2 is responsible for high level of NO production under pathophysiological conditions such as an infection." (PMID 32459575, 2020). "NOS1 and NOS3 are constitutively expressed, and produce small quantity of NO, while NOS2 generates NO for extended periods of time, at high concentrations, being key as regulator and effector during inflammation and infection." (PMID 38841361, 2024). "We demonstrate that, even without induced active infection, different baseline microbiota colonization patterns result in distinct inflammatory profiles in the brain as evidenced by the elevated expression levels of Nos1 in MPI-L mice and Il-1β and Tnf in GF mice." (PMID 29615691, 2018). "We observed significantly increased expression of NOS2, but not NOS1 or NOS3, in response to 12 h of SH0165 infection." (PMID 31766159, 2019).
neurodegenerative disease (19 papers, 2014 to 2026). A disorder of the central nervous system characterized by gradual and progressive loss of neural tissue and neurologic function. "Importantly, all of these synaptic regulators (Nos1, Lrp8, Argef2, Sema5b) and other significantly altered splice variants (e.g., Adipor2, Mapk14, Smarca4, Sort1, Mapt) have been linked to AD and other neurodegenerative diseases." (PMID 37819053, 2023). "Therefore, mis-splicing of NOS1 could lead to increased ROS, and thus increased protein mis-folding and aggregation associated with neurodegenerative diseases (i.e. AD)." (PMID 30704480, 2019).
psychiatric disorder (17 papers, 2009 to 2026). A disorder characterized by behavioral and/or psychological abnormalities, often accompanied by physical symptoms. "In particular, because NO signaling has been targeted pharmacologically for other indications, understanding NOS1 dysfunction in psychiatric disorders has tremendous potential to lead to the repurposing of efficacious, tested agents to treat these disorders." (PMID 25101118, 2014). "The genetic and mechanistic evidence presented in this review suggest that NOS1 may similarly play a role in multiple psychiatric disorders." (PMID 25101118, 2014). "Together, these data suggest that the potential involvement of NOS1 in multiple psychiatric disorders may be mediated in part via interactions with VGCCs." (PMID 25101118, 2014). "Together, these findings converge on the possibility that NOS1 dysfunction in pyramidal neurons of the ACC and Broca’s area may contribute to distinct psychiatric disorders that affect higher cognitive abilities." (PMID 25101118, 2014).
neurological disorders (12 papers, 2017 to 2026). "Growing evidence suggests that Nitric oxide synthase 1 (NOS1) is involved in neural development and neurologic diseases." (PMID 29940959, 2018). "Cc can treat Mn-induced nervous system diseases through targets such as CASP9, PTGS2, NOS1, and NOS2." (PMID 37904435, 2023). "Our network analysis demonstrated that the most highly correlated targets between Mn-induced nervous system disease-related genes and Cc compound-related genes were CASP9, PTGS2, NOS1 and NOS2, which are primarily involved in oxidative stress and inflammation." (PMID 37904435, 2023).
heart disease (7 papers, 2009 to 2025). "An interesting target of identified miR-4492 is CAPON (nitric oxide synthase 1 adapter protein), which interacts with NOS1 and plays a role in psychiatric as well as heart diseases." (PMID 39201485, 2024). "We conclude that NOS1 is a potentially important therapeutic target for the treatment of arrhythmogenic heart disease." (PMID 24498331, 2014).
Bacterial infections (2 papers, 2022 to 2024). "Bacterial infections upregulated the transcription of nitric oxide synthase 1/2 (NOS1/2), CanA and AMP genes and increased NO concentration in larval hemolymph." (PMID 35663981, 2022).
colorectal (1 paper, 2026). "Thus, we sought to elucidate the role of NOS1 methylation in colorectal carcinogenesis, which is essential for understanding disease pathology." (PMID 42048609, 2026).
inflammation (1 paper, 2023). Aberrant reaction of the microcirculation characterized by movement of fluid and leukocytes from the blood into extravascular tissues. "EGCG inhibition of NF-κB also promotes the inhibition of aberrant NO production characterized in neuroinflammation, as evidenced in the downregulation of NOS1 (which is implicated in vascular inflammation and is connected to the NF-kB pathway)." (PMID 37190597, 2023).
overlap syndrome (1 paper, 2022). "The aim was to study the association of allelic variants and genotypes of the single nucleotide variant (SNV) rs3782218 of the NOS1 gene with the TTH and AH overlap syndrome development in middle age adults." (PMID 36292708, 2022).
vasculopathy (1 paper, 2025). "Our findings revealed that protein levels of eNOS and mRNA levels of Nos1 were decreased in APP/PS1 mice, indicating possible vasculopathy in the hippocampal region." (PMID 41164084, 2025).